ALDH3A1 (aldehyde dehydrogenase 3 family member A1)
Diseases named in the same sentence as ALDH3A1 in open-access papers (continued):
Sharing a sentence is not in itself a finding about the gene and the disease.
cancer (68 papers, 2008 to 2026). A tumor composed of atypical neoplastic, often pleomorphic cells that invade other tissues. "ALDH3A1, a detoxifying aldehyde dehydrogenase isoform implicated in cancer and neurodegeneration, is a promising yet underexplored therapeutic target." (PMID 42216908, 2026). "As a member of the aldehyde dehydrogenase family, ALDH3A1 has been associated with cancer stem cell properties and chemoresistance, and this study is the first to confirm its role in radioresistance." (PMID 41306526, 2025). "Aldehyde dehydrogenase 3 family member A1 (ALDH3A1), an enzyme involved in drug metabolism, is negatively correlated with peroxisome proliferator-activated receptor γ (PPARγ) and is implicated in cancer cell resistance to anticancer drugs." (PMID 41278297, 2025). "Unlike ALDH3A2, aldehyde dehydrogenase 1 family member A1 (ALDH1A1), 1 family member B1 (ALDH1B1), and 3 family member A1 (ALDH3A1) expression levels are elevated in other malignant tumors and associated with poorer survival outcomes." (PMID 40923024, 2025). "Recent research has showed that the expression of ALDH3A1 was upregulated in several cancer types and demonstrated clear association between ALDH3A1 and cancer progression." (PMID 38191346, 2024). "In recent years, ALDH3A1 has been shown to be upregulated in several cancer types and associated with poor clinical outcomes 17-19." (PMID 32201532, 2020). "Recently, many studies have revealed that ALDH3A1 can be used as a biomarker to predict the prognosis of malignant tumors, and have been associated with different clinical outcomes in a wide variety of human malignancies 17-21." (PMID 32201532, 2020). "Not surprisingly, several ALDH isoforms other than ALDH1A1 have been proved being associated with certain cancers, e.g., ALDH3A1 in lung cancer and prostate cancer and ALDH5A1 in breast cancer." (PMID 30220009, 2019). "Increased levels of ALDH1A1 and ALDH3A1 in various human cancers have been associated with enhanced tumorigenic ability, chemo-resistance, and poor prognosis." (PMID 28978015, 2017). "Although ALDH3A1 is known to regulate cell function and cancer prognosis, the effects and underlying mechanisms of chronic stress states remain unclear." (PMID 38191346, 2024). "However, the association of ALDH3A1 with E-cadherin expression has been previously studied in cancer cells." (PMID 36982917, 2023). "In light of the magnitude of the observed functional changes caused by ALDH3A1 overexpression in cancer cell lines, it appears plausible that the enzyme causes extensive cell redox metabolism reprogramming (for example, reduced 4HNE adducts), rather than being a mere marker of stemness." (PMID 31817719, 2019). "Our results show that the inhibition of ALDH enzymes including ALDH3A1 by dyclonine cooperatively enhances the efficacy of xCT-targeted therapy by promoting accumulation of the toxic aldehyde 4-HNE in GSH deficiency-resistant cancer cells." (PMID 30333913, 2018). "We found that the mRNA and protein levels of ALDH3A1 decreased after GOT1 knockdown in cancer cells, which was consistent with the sequencing results." (PMID 41327788, 2025). "A substantial body of evidence indicates that the aberrant overexpression of ALDH3A1 is significantly correlated with the progression of malignant tumors." (PMID 41228459, 2025). "Transcription factors TP63, SOX2, and KLF5 have been demonstrated to influence chromatin dynamics and contribute to cancer-specific gene ALDH3A1 inactivation in ESCC." (PMID 40523880, 2025). "The immunohistochemistry results of human samples indicated that ALDH3A1 expression was higher in cancer tissues than in normal tissues." (PMID 41327788, 2025). "Mechanistically, melatonin upregulates the core clock protein BMAL1, which transcriptionally represses its downstream target ALDH3A1, thereby effectively blocking the glycolytic program in tumor cells and suppressing cancer progression." (PMID 41228459, 2025).
cancer (continued). "ALDH3A1 has been described to present high levels in cancer cells and low levels in normal pneumocytes." (PMID 39997396, 2025). "Epidermal growth factor receptor (EGFR) and aldehyde dehydrogenase 3 family member A1 (ALDH3A1) play important roles in cancer stem cell metabolism." (PMID 39513911, 2024). "Our results showed that the gene ALDH3A1, associated with Ferroptosis biomarkers, and the gene SOX2, involved in cancer stemness, were both upregulated." (PMID 38206305, 2024). "A recent study discovered that cancer stem‐like cells (CSCs) enhanced PD‐L1 expression via ALDH3A1 isozyme to promote immune evasion in lung tumors." (PMID 39036344, 2024). "Antecedent researches have reported that ALDH3A1 plays a key role in the malignant behavior of cancers through stimulating signaling pathways." (PMID 38191346, 2024). "Considering the aggressiveness and the resistant phenotype of these cells, ALDH3A1 has emerged as a valuable marker in cancer research." (PMID 37021113, 2023). "ALDH3A1, as an important member of the acetaldehyde dehydrogenase superfamily, plays an important role in the occurrence and development of malignant tumors." (PMID 38099574, 2023). "LDHA, ALDH3B1, and ALDH3A1 are all connected to the genesis and development of various cancers and play a role in mitochondrial energy metabolism." (PMID 36814901, 2023). "In recent years, ALDH3A1 has been shown to be upregulated in several cancer types, for example, GC,101 lung cancer, HCC,191 colon cancer, PCa193 and can be used as a biomarker to predict poor clinical outcomes." (PMID 36694633, 2023). "P25 TRAMP CRIPSCs also had upregulated genes related to cancer development and drug resistance, such as Aldh3a1, Ly6d, Il33, Dsg3, and Col17a1." (PMID 35841025, 2022). "In pancreatic cancer, ALDH3A1 was a critical gene that affected cancer cell proliferation and drug resistance." (PMID 34234849, 2021). "Overall, our work highlights that ALDH3A1 is highly expressed in M1 LUAD patients and associated with cancer stem cell property." (PMID 34234849, 2021). "The majority were localized to cluster lungH1 and expressed lower levels of metastatic cancer cell markers (ALDH3A1, VIM, TCEAL9)." (PMID 34579762, 2021). "Although ALDH3A1 was screened and presented a predictive role for tumor progression in different cancers, few studies identified this phenomenon." (PMID 34234849, 2021). "Since ALDH3A1 plays a critical role in normal cells, efforts to understanding this role in cancers have largely been reported." (PMID 34234849, 2021). "We showed that ALDH3A1 has an important role in lipid catabolism by catalyzing the production of fatty aldehydes by lipid peroxidation in cancer cells." (PMID 32882923, 2020). "Two differentially expressed genes, Id2 and Aldh3a1, were validated in in-vivo models using mouse and human cancer cell lines." (PMID 30642388, 2019). "Inhibition of ALDH3A1 by knock down using siRNA of ALDH3A1 resulted in significantly reduced ATP production by cancer cells, leading to apoptosis." (PMID 31705020, 2019). "Of relevance to this work, the ALDH3A1 isozyme plays an important role in the survival, metastasis, and drug resistance of cancer cells, being mechanistically involved in cancer stem cell expansion and differentiation." (PMID 31817719, 2019). "Of note, specific inhibitors of ALDH3A1 have been developed and shown to enhance the sensitivity of cancer cells to the alkylating agent cyclophosphamide." (PMID 29854309, 2018). "The ALDH3A1 inhibitor dyclonine is thus cytotoxic only in the presence of accumulated 4-HNE in xCT inhibitor–treated cancer cells." (PMID 30333913, 2018). "The expression of the ALDH isoform 3A1 (ALDH3A1) has been used as a cancer stem/progenitor marker from multiple organs, including colon and liver." (PMID 24884630, 2014).
cancer (continued). "The results of RNAseq analyses, qPCR, and enzyme activity studies consistently show that R cells express the cancer stem cell marker ALDH3A1." (PMID 24884630, 2014). "ALDH3A1 has been identified as an important enzyme serving as a marker of various types of cancer stem cells." (PMID 24884630, 2014). "Specifically, ALDH1A1 and ALDH3A1 have been used as markers to isolate normal and cancer stem cells and have a potential functional role in normal and cancer stem cells." (PMID 24405526, 2013). "ALDH3A1 plays roles in the maintenance of cancer stem cells and cisplatin resistance." (PMID 40643470, 2025). "Aldehyde dehydrogenase 3A1 (ALDH3A1) is a potential downstream target that may contribute to the disruption of glycolysis in cancer cells." (PMID 41327788, 2025). "ALDH3A1 and NECTIN4 have been previously linked to cancer pathogenesis." (PMID 39969205, 2025). "In addition, the IHC analysis of GC patient specimens demonstrates that ALDH3A1 expression is closely correlated to clinical features, including cancer dysplasia and grade, LNM, and cancer stage." (PMID 36694633, 2023). "Finally, ALDH3A1 has been characterized as a potential cancer stem cell (CSC) marker in various types of solid tumor malignancies." (PMID 37021113, 2023). "Although ALDH3A1 has multifaceted functions in both normal and cancer homeostasis, its modes of action are currently unknown." (PMID 37021113, 2023). "ALDH3A1 is known as an important marker for cancer stem cells." (PMID 37730658, 2023). "ALDH3A1 showed a positive correlation with cancer stem cell and EMT." (PMID 34234849, 2021). "We, therefore, explored the potential role of ALDH3A1 in mediating cancer cell proliferation." (PMID 34234849, 2021). "In prostate cancer, ALDH3A1 was expressed in cancer stem cells related to drug-resistance." (PMID 34234849, 2021). "Over-expression of ALDH3A1 in cancer cells correlates with an increased chemo-resistance to drugs." (PMID 33005401, 2020). "However, in the cancer tissue, ALDH3A1 was less expressed at different levels, even in some cases, ALDH3A1 expression totally disappeared." (PMID 32201532, 2020). "Therefore, an increase of 4-hydroxynonenal by knock down of ALDH3A1 was inversely correlated with ATP production in cancer cells." (PMID 32882923, 2020). "Therefore, targeting ALDH3A1 and mitochondrial complex I using gossypol and phenformin results in almost complete depletion of ATP, which downregulates cancer cell growth through mTOR inhibition and further induces cell death by disturbing homeostasis." (PMID 31705020, 2019). "In both preclinical and clinical studies it has been reported that high levels of ALDH3A1 promote chemoresistance towards various common anti-cancer drugs and could be correlated with poor clinical prognosis." (PMID 29854309, 2018). "Inhibition of ALDH3A1 might thus enhance the efficacy of xCT-targeted therapy in multiple types of cancer." (PMID 30333913, 2018). "By inhibiting ALDH1A1 and ALDH3A1, it may be possible to overcome resistance to chemotherapy and enhance the efficacy of existing cancer treatments, providing new avenues for combating resistant cancer types." (PMID 39534872, 2024). "Besides, following ALDH3A1 knockdown, a rapid decline of Ki67 expression suggested that ALDH3A1 might regulate cancer cells proliferation." (PMID 34234849, 2021). "Moreover, we noticed that three upregulated genes in the high-risk group, ALDH3A1, ALDH3B2, and ADH7, participate in the cytochrome P450-mediated metabolism of trichloroethylene; trichloroethylene is an organic chemical, exposure to which can cause cancer." (PMID 32858528, 2020). "In ESCA, ALDH3A1 is regulated by the core regulatory circuitry transcription factors TP63, SOX2 and KLF5 and is involved in the proliferation of cancer cells." (PMID 40529228, 2025). "This study further identifies ALDH3A1 as a key downstream effector molecule of BMAL1 and a potential target for cancer therapy." (PMID 41228459, 2025).
cancer (continued). "We identified dozens of proteins with high protein level variability across the different cancer regions, including CYC1 and ALDH3A1, suggesting spatial differences in metabolic activity and oxidative stress adaptation." (PMID 41418981, 2025). "Previous studies have demonstrated that ALDH3A1, a member of the ALDH superfamily, enhances DNA damage repair and mediates chemoresistance through eliminating cellular ROS in cancer cells." (PMID 39669976, 2024). "ALDH3A1 inhibitors such as dyclonine, CB7, and CB29 have all been shown to enhance cancer cell sensitivity to sulfasalazine and cyclophosphamide, respectively." (PMID 38612911, 2024). "Studies have demonstrated that ALDH3A1 expression is closely related to changes in the biological behavior of tumor cells, such as epithelial mesenchymal transition (EMT), metastasis, and cancer stem cell expansion, impairing immune surveillance." (PMID 37730658, 2023). "Recently, isoform‐specific inhibitors are under investigation in cancer research, and some inhibitors can target ALDH1A1, ALDH2, and ALDH3A1." (PMID 36694633, 2023). "Metabolic enzymes AKR1B10, ALDH3A1, and ALDH1A1 have been reported by our group and others as leading candidate biomarkers for multiple cancer types, including lung." (PMID 37760474, 2023). "Evaluation of cancer stemness properties in residual tumor tissue after treatment with BTZ alone revealed increased CD133 expression to 188.7 ± 26.7% (P < 0.001) and ALDH3A1 expression to 146.5 ± 24.7% of controls (P < 0.005)." (PMID 32868872, 2020). "Many other cancer-related genes showed up differentially expressed in PDAC, including MUC2, MUC5B, MUC13, ALDH3A1, CDCA7, and CCL2." (PMID 31379917, 2019). "Furthermore, we found that several dyclonine analogs were also able to enhance the cytotoxic action of xCT or GSH synthesis inhibitors, suggesting that the covalent inhibition of ALDH enzymes including ALDH3A1 might sensitize sulfasalazine-resistant cancer cells to xCT-targeted therapy." (PMID 30333913, 2018). "All together, these results suggest that inhibition of NRF2 is related with the enhancement of the sensitivity of these cells to chemotherapeutic agents and the expression of cancer cell stemness biomarker as ALDH1A1 and ALDH3A1." (PMID 28671577, 2017). "Our results suggest that the inhibition of both ALDH1A1 and ALDH3A1, and particularly their reducing-agent-dependent NAD+ reduction activity, should be viewed as targets for the development of anti-cancer therapies." (PMID 28978015, 2017). "The representative genes used were ALDH3A1, TNS4, CLDN2, and ALDKETO, and are known to play important roles in cancer cell de-differentiation, migration, invasion, proliferation and apoptosis suppression." (PMID 24884630, 2014). "The expression of some genes, such as ALDH3A1, TNS4, CLDN2, and AKR1B10, which are known to play important roles in cancer cell migration, invasion, proliferation and apoptosis, were increased in HCT-8 R cells." (PMID 24884630, 2014). "However, the role of specific ALDH isoforms, such as ALDH1A1, ALDH1A3, ALDH2, and ALDH3A1, as CSC markers has shifted attention towards developing targeted inhibitors to prevent cancer progression." (PMID 38612911, 2024). "Apart from its metabolic role though, several lines of evidence suggest that ALDH3A1 is a multifaceted protein with variable non-catalytic properties in both normal and cancer homeostasis." (PMID 37021113, 2023). "Notably, S100A8 and ALDH3A1 did not demonstrate statistical significance in our data, despite the publication reporting a notable decrease in cancer incidence." (PMID 37553345, 2023). "In the present study, we found that cancer-specific metabolic characteristics include spontaneous peroxidation of fatty acids (such as linoleic acid and arachidonic acid) by ROS, which supplies the fatty aldehyde HNE as an electron donor; this is then converted to fatty acid HNA and NADH by ALDH3A1." (PMID 31705020, 2019).
cancer (continued). "Given the importance of ROS generation to the mechanism of mitoKv1.3 inhibitor mediated cell death, it is not surprising to see that cancer cells resistant to PCARBTP upregulated the antioxidant system (GSR, GSTO1, GSTA2, ALDH3A1)." (PMID 35681598, 2022).